NFKBIA (NFKB inhibitor alpha)
Diseases named in the same sentence as NFKBIA in open-access papers (continued):
Sharing a sentence is not in itself a finding about the gene and the disease.
cancer (continued). "Such “onco-miRNAs” have also been demonstrated in PDAC: miR-196a promotes cancer progression by targeting NFKBIA, and miRNA-126 and 148a inhibit cancer cell growth by down-regulating CDC25B and ADAM9, respectively." (PMID 25742499, 2015). "Sequestration by IκBα is important for modulating NF-κB signaling as functional polymorphisms in the NFKBIA promoter and 3′ untranslated regions are significantly associated with cancers, such as HBV-induced hepatocarcinogenesis." (PMID 38033031, 2023). "Moreover, the analyses showed the existence of a distinct metabolic profiles in NFKBIA amplified cancers." (PMID 33863364, 2021). "NFKBIA −881G might alter the binding ability of RORα, which plays a potential role in cancer development." (PMID 22509384, 2012). "Therefore, the accumulation of NFKBIA within the nucleus due to XPO1 inhibition in TNBC cells may explain the reduction in NF-kB transcriptional activity similar to that seen in other cancer contexts." (PMID 39682167, 2024). "Interestingly, we found that the significant association of cisplatin sensitivity with NFKBIA expression was specific to cancer cell lines from CNS tissues, not from other tissue types." (PMID 37062025, 2023). "Therefore, using The Cancer Genome Atlas copy number alteration and RNA-Seq data from 398 patients, we evaluated the association between the expression and dosage of NFKBIA, which encodes IκBα, and the overall malignancy of LGGs." (PMID 27052952, 2016). "Most of the activated TFs are involved in cancer progression through the TIME, such as the NFκB family (NFKB1, NFKBIA, and RELA) and the STAT family (STAT1, STAT2, and STAT6), which are critical in M1 and M2 macrophage polarization." (PMID 36230879, 2022). "Through the cell experiment results, we found that NFKBIA played a protective role, while INHBA played the pro-cancer role." (PMID 35999846, 2022). "Knockouts of some “cancer drivers” of DLBCL, including BCL2, BCL6, NFKBIA and CD70, showed only modest promotional effects on cell proliferation." (PMID 33911074, 2021). "Consistently, the knockout of HMOX1 suppresses, whereas the overexpression of HMOX1 promotes, ferroptotic cancer cell death induced by erastin or BAY 11-7085 (NFKB inhibitor alpha [NFKBIA/IKBA] inhibitor)." (PMID 33117818, 2020). "In addition to enhanced phosphorylation, a heterozygous deletion of NFKBIA (IκBα) has been reported by Bredel and coworkers in 28% of GBM and 22% of cancer stem-like cells." (PMID 35983068, 2022). "These alterations in NFKBIA and MYC are shown to potentially be prognostic in some cancer types." (PMID 32099096, 2020).
bacterial infection (12 papers, 2010 to 2025). "Several genes identified through our experimental approach have been linked to roles in host responses to bacterial infection (CCL5, ITLN1), immune modulation (ZFP36, NFKBIA) and damage (EDN1) during PD or during episodes of PD peritonitis." (PMID 28542390, 2017). "In this article, we shortlisted activated target genes in monocytes during acute bacterial infection, including VNN1, NLRC4, CYP1B1, PFKFB3, LILRA5, NFKBIA or NFKBIZ." (PMID 40581066, 2025). "Other monocyte informative genes were also activated in patients with bacterial infection including NLRC4, CYP1B1, PFKFB3, LILRA5, NFKBIA, and NFKBIZ." (PMID 40581066, 2025). "Although 94 predicted upstream regulators were conserved amongst the studies, 14 were found only in the endometrium of pregnant healthy cows, and 5 were found only in cows following bacterial infection, including AIRE, NFKBIA, and DUSP1." (PMID 35358206, 2022). "Six immune-related genes were potentially targeted by gga-miR-1416-5p including BCL10, NFKBIA and TLR21, which were important in the response to bacterial infection." (PMID 28086873, 2017).
hematologic malignancies (3 papers, 2016 to 2021). "Moreover, different hematological diseases have been linked to the presence of polymorphisms in the NFKBIA gene likely associated with altered protein activity or gene expression." (PMID 34572464, 2021). "Mutations in NFKBIA were also found in around 22% of patients with Gray zone lymphoma (GZL), a rare hematological disease with features intermediate between large B-cell lymphoma (LBCL) and classical HL." (PMID 34572464, 2021).
endocrine system diseases (1 paper, 2023). "Pirin, RELA (p65) and NFKBIA are significantly associated with endocrine system diseases." (PMID 38033031, 2023).
heart disease (1 paper, 2021). "NFKBIA encodes a potent inhibitor of NF-κB58, which mediates activation of the inflammatory response with important consequences in heart disease." (PMID 33911098, 2021).
NFKBIA also shares sentences with these, for which no sentence is quoted: colitis (61 papers); multiple myeloma (27); inflammation (18); leukemia (13); liver fibrosis (13); Cerebral ischemia (12); injury (11); ischemia (10); lupus (10); Stroke (10); cardiac hypertrophy (9); cervical cancer (9); periodontitis (9); Arthritis (8); Parkinson disease (8); pulmonary fibrosis (8); bladder cancer (7); cardiovascular diseases (7); Cognitive impairment (7); depression (7); gastritis (7); kidney (7); metabolic syndrome (7); nasopharyngeal carcinoma (7); renal fibrosis (7); esophageal squamous cell carcinoma (6); gastric ulcer (6); squamous cell carcinoma (6); Alzheimer disease (5); dermatitis (5).
A further 234 diseases each share a sentence with NFKBIA in 5 papers or fewer.